CASP1 (caspase 1)
Diseases named in the same sentence as CASP1 in open-access papers (continued):
Sharing a sentence is not in itself a finding about the gene and the disease.
Listeria infection (7 papers, 2011 to 2025). "Surprisingly, chronic infection with MHV68 complemented the immunodeficiency of HOIL-1, IL-6, Caspase-1 and Caspase-1;Caspase-11-deficient mice following Listeria infection." (PMID 25599590, 2015). "IL-6, Caspase-1 and Caspase-1;Caspase-11-deficient mice were also protected from lethality following Listeria infection by chronic MHV68 infection." (PMID 25599590, 2015). "We further show that chronic infection with MHV68 rescued HOIL-1, IL-6, Caspase-1 and Caspase-1;Caspase-11-deficient mice from lethal Listeria infection, thereby masking the genetic immunodeficiency observed in MHV68-negative mice." (PMID 25599590, 2015). "Only at lower, more physiological doses [MOI (multiplicity of infection) 30 to 40], Listeria infection activated the NLRP3/caspase-1 pathway and the processed caspase-1 p20 product became evident by immunoblotting." (PMID 40053580, 2025). "Previous work has demonstrated that Ch25h-deficient macrophages overproduce IL-1β and have deregulated caspase-1-activating inflammasome activity in response to Listeria monocytogenes infection or LPS stimulation." (PMID 36831236, 2023). "In line with this, a previous study demonstrated that inhibition of the NF-κB and ERK pathways reduces caspase-1 activation, resulting in decreased IL−1β secretion during Listeria monocytogenes infection." (PMID 37958940, 2023). "However, at this time point, bacterial burden in spleen was significantly higher in RIPK3–/–, Casp-1/11–/–, and Casp-1/11–/–/RIPK3–/– double deficient in comparison to WT mice, suggesting that both RIPK3 and Casp-1/11 are important to control the early phase of listeria infection." (PMID 32328060, 2020). "To determine whether the viral complementation of immunodeficiency was unique to HOIL-1, we latently infected IL-6, Caspase-1-deficient and Caspase-1;Caspase-11-double-deficient mice, which survive MHV68 infection but are all highly susceptible to Listeria infection." (PMID 25599590, 2015). "In the case of Salmonella and Listeria infections, necrosis induction requires the caspase-1-mediated inflammasome of NLRP3, although the cascade of events downstream of caspase-1 that are responsible for cell death remains unknown." (PMID 21740493, 2011).
renal cell carcinoma (7 papers, 2020 to 2025). "As a natural compound, ursolic acid upregulates expression of NLRP3 in RCC and then activates caspase-1, which eventually causes prolapse of renal cell carcinoma and inhibits tumour growth." (PMID 36702978, 2023). "In addition, recent studies have shown that inhibition of BRD4 in RCC suppresses cell proliferation as well as epithelial–mesenchymal transition (EMT) progression and plays an anti-tumour role in renal cell carcinoma by activating the NF-κB-NLRP3-Caspase-1 signalling pathway." (PMID 36702978, 2023). "In renal cell carcinoma, the BRD4 knockdown and JQ1 treatment suppressed the epithelial-to-mesenchymal transition (EMT) and tumor growth progression via caspase-1-dependent pyroptosis in vitro and in vivo." (PMID 38136175, 2023). "In renal cell carcinomas, inhibition of BRD4 by genetic knockdown or JQ1 prevents cell proliferation and EMT, and induces NF-κB-NLRP3-Caspase 1-dependent pyroptosis, providing evidence for BRD4 being a potential target and JQ1 as a therapeutic agent for renal cell carcinomas." (PMID 33343366, 2020). "Recently, JQ1 has been shown to induce pyroptosis in renal cell carcinoma (RCC) via the activation of NF-κB, which subsequently activates the NLRP3 inflammasome, leading to caspase-1-dependent pyroptosis." (PMID 40149884, 2025). "BRD4 is upregulated in the renal cell carcinoma (RCC) cell lines 786-O and ACHN but downregulates caspase-1." (PMID 34522213, 2021).
auto-inflammatory syndromes (6 papers, 2013 to 2023). "Inflammasome mutations can lead to inappropriate caspase-1 activation, which is associated with autoinflammatory syndromes." (PMID 35008798, 2021). "Inflammasomes were activated in auto-inflammatory syndrome patients, who also exhibited conversion of pro-IL-1β to an active form to secret by caspase 1 activity." (PMID 30361689, 2018).
breast tumor (6 papers, 2012 to 2025). "The obtained results highlighted the good biocompatibility and capacity of the proposed 3D hydrogels to facilitate 5-fluorouracil’s therapeutic efficacy and to implicitly stimulate caspase-1 activity in breast tumor cells." (PMID 39940603, 2025). "The scaffolds’ composition facilitated normal breast cells’ viability and proliferation, while the presence of PTX into the scaffolds’ compositions stimulated caspase-1 activity, IL-1β secretion, and ROS production by the breast tumor cells." (PMID 39940603, 2025). "Other groups have found that knocking out Nlrp3 and Casp1 in mice significantly reduces the growth of primary breast tumours and lung metastases compared with wild-type mice." (PMID 36230739, 2022). "Analysis revealed a significant up-regulation in the expression of genes from the NLRP3 inflammasome pathway (NLRP3, PYCARD, CASP1, and IL-1β) in the stroma of human breast tumours compared with normal stroma, suggesting a functional role for this pathway in tumour progression." (PMID 31558756, 2019).
cardiomyopathy (6 papers, 2020 to 2025). A disease of the heart muscle or myocardium proper. "Change of NLRP1 and CASP1 has also been demonstrated to be associated with cardiomyopathy." (PMID 37724419, 2023). "The NLRP3/Caspase 1/IL-1 pathway is a key mediator of cardiomyopathy, doxorubicin-induced cardiotoxicity, and vascular diseases." (PMID 33086484, 2020).
cholestasis (6 papers, 2016 to 2024). Impairment of the bile flow caused by obstruction within the liver, or outside the liver in the bile duct system. "Subsequently, the elevation of TNFRSF12A triggers hepatocyte pyroptosis by the NFκB/Caspase-1/GSDMD signaling in cholestasis." (PMID 36690641, 2023). "Previous studies in the context of cholestasis demonstrated that bile acids induce TNFRSF12A expression, subsequently initiating hepatocyte pyroptosis through the nuclear factor κB (NF-κB)/CASP1/gasdermin (GSDMD) signaling pathway." (PMID 39232561, 2024).
cryopyrin-associated periodic syndrome (6 papers, 2014 to 2025). Cryopyrin associated periodic syndrome (CAPS) defines a group of autoinflammatory diseases, characterized by recurrent episodes of systemic inflammatory attacks in the absence of infection or autoimmune disease. "The NLRP3 inflammasome plays an important role in the pathogenesis of the Cryopyrin-Associated Periodic Syndrome (CAPS) activating caspase-1." (PMID 33562758, 2021). "Recombinant oligomeric protein particles composed of the adaptor ASC or the p.D303N mutant form of NLRP3 associated with cryopyrin-associated periodic syndromes (CAPS) stimulate further activation of caspase-1 extracellularly, as well as intracellularly after phagocytosis by surrounding macrophages." (PMID 27842563, 2016). "Caspase-1 is also a critical putative target in patients with cryopyrin-associated periodic syndromes (CAPS)." (PMID 24762050, 2014). "Cryopyrin-Associated Periodic Syndrome (CAPS) represents autosomal dominant gain of function mutations that results in over activation of the inflammasome and increased conversion of pro-caspase-1 to activate caspase-1 and this results in increased IL-1β and IL-18 protein levels." (PMID 35003136, 2021).
cyst (6 papers, 2016 to 2024). A sac-like closed membranous structure that may be empty or contain fluid or amorphous material. "In the peritoneum, we saw a ~3-fold increase in parasite burden in the Cx3cr1+Casp1 KO mice compared to control mice, which was associated with a greater cyst burden in the brains of these mice at 6 weeks post-infection (6wpi)." (PMID 39446964, 2024). "Caspase-1 cleavage activates inflammatory cytokines, including IL-18, and active IL-18 is highly expressed in the kidneys, cyst fluid, and urine of ADPKD patients and animal models, indicating that caspase-1 is active in cyst cells." (PMID 37579949, 2023). "To further evaluate inflammasome activation in the kidneys of ADPKD patients, we measured the levels of IL-1β and IL-18, which are primary products of activated Caspase-1, in the cyst fluids collected from 12 different patients." (PMID 36523654, 2022). "Collectively, these results provide evidence for the first time that the activated Caspase-1/inflammasome promotes cyst expansion and disease progression in PKD, particularly in females." (PMID 36523654, 2022). "In the studies reported here, knockout of Casp1 slowed cyst expansion and disease progression, but the effects were statistically significant only in females." (PMID 36523654, 2022). "We also show for the first time that knockout of Caspase-1 slows cyst expansion and disease progression specifically in females suggesting a significant sex difference in the inflammatory environment of these mice." (PMID 36523654, 2022). "Another question to be explored is whether renal activation of Caspase-1/inflammasome in PKD mice always leads to accelerated cyst formation and disease progression." (PMID 36523654, 2022). "In addition to an increased overall cyst burden, caspase-1/11 KO mice had more instances of clusters of parasite cysts compared to WT, likely indicating a lack of parasite control in areas of parasite reactivation." (PMID 32703941, 2020). "Thus, all the caspase genes examined were enhanced in the AQP11(−/−) kidney before (at two weeks) and after (at eight weeks) cyst formation with remarkably higher expressions of Casp1, Casp4 and Casp12." (PMID 27916883, 2016). "Also, it is worth considering whether activated Caspase-1 is sufficient to promote de novo cyst formation in the absence of mutations that cause PKD." (PMID 36523654, 2022). "Such Caspase-1-independent inflammatory pathways in RC/RC males may be related to the reported amplified response to renal ischemic injury that occurs in males, which could be relevant in PKD because of the ongoing ischemic and mechanical injury arising from vascular compression and cyst expansion." (PMID 36523654, 2022).
diabetic retinopathy (6 papers, 2021 to 2025). "Future studies will also have to identify how other cytokines such as TNFα that have been associated with the development of diabetic retinopathy influence the regulation of the caspase-1/IL-β/IL-1R1 feedback signaling." (PMID 39483336, 2024). "Our previous work has indicated that caspase-1 is activated throughout the progression of diabetic retinopathy in STZ and galactosemic mice." (PMID 39483336, 2024). "This new study provides novel mechanistic insights into the process of chronic caspase-1 activation and IL-β production in diabetic retinopathy." (PMID 39483336, 2024). "We conclude that any intervention in caspase-1/IL-1β/IL-1R1 feedback signaling presents novel therapeutic options for the treatment of diabetic retinopathy." (PMID 39483336, 2024). "On the other hand, downregulation of LCN2 was shown to significantly inhibit cell migration, invasion, angiopoiesis, and pyroptosis regulated by caspase-1, thus attenuating the progression of diabetic retinopathy." (PMID 37371057, 2023). "By inhibiting the activation of NLRP3, ASC, caspase-1, and NF-κB to reduce the production of IL-1β and IL-18, propelling RvD1 to be expected an effective means to alleviate the progression of diabetic retinopathy." (PMID 33967796, 2021). "Intervention in the caspase-1/IL-1β/IL-1R1 feedback signaling by inhibition of caspase-1 as shown in this study or by the IL-1 receptor as we previously reported prevents Müller cell death in diabetic retinopathy demonstrating the importance of this signaling pathway to Müller cell viability." (PMID 39483336, 2024). "Literature was reviewed from common science libraries PubMed and Embase using various combinations of the search terms “diabetic retinopathy,” “HIF-1a,” “caspase-1,” and “IL-1B”." (PMID 37637673, 2023). "Although there are a couple of drugs on the market that target the caspase-1/IL-1β complex none of them have been tested in the context of diabetic retinopathy." (PMID 39483336, 2024). "Studies in diabetic retinopathy indicate that Cx43 hemichannels lie upstream of inflammasome activity, with aberrant ATP release activating the P2 × 7 receptor, NLRP3 assembly and resultant caspase 1-mediated cleavage of IL1ß and IL18." (PMID 38970061, 2024).
esophageal cancer (6 papers, 2017 to 2026). A primary or metastatic malignant neoplasm involving the esophagus. "Furthermore, caspase-1-derived pyroptosis was associated with esophageal cancer." (PMID 38221934, 2024). "In esophageal cancer, betulinic acid elicited caspase-1-dependent pyroptosis." (PMID 33718226, 2021). "In esophageal cancer, miR-497 inhibited PELP1 to activated caspase-1-dependent pyroptosis." (PMID 33718226, 2021). "However, we could not identify reports investigating chemosensitivity with regard to TCF, Src, caspase-1, VDR, BLIMP-1, PDGFR, and IL-1 in esophageal cancer." (PMID 29136005, 2017).
familial cold autoinflammatory syndrome (6 papers, 2015 to 2022). Familial cold urticaria (FCAS) is the mildest form of cryopyrin-associated periodic syndrome (CAPS) and is characterized by recurrent episodes of urticaria-like skin rash triggered by exposure to cold associated with low-grade fever, general malaise, eye redness and arthralgia/myalgia. "Caspase-1 inhibition prevents familial cold autoinflammatory syndrome-associated NLRP3 mutant-mediated inflammasome assembly." (PMID 35616535, 2022). "Additionally, familial cold autoinflammatory syndrome (FCAS) in one Japanese family was found to be due to a missense mutation in NLRC4 causing enhanced activation of caspase-1 along with increased production of IL-1β." (PMID 33494299, 2021).
gastric ulcer (6 papers, 2016 to 2025). An ulcerated lesion in the mucosal surface of the stomach. "NLRP3 inflammasome is an intracellular complex associated with inflammatory response, which induces the production of mature IL-1β and triggers apoptosis through caspase-1 cleavage, playing an important role in the formation of gastric ulcer." (PMID 38807640, 2024). "FCPP aqueous extract might prevent gastric ulcers by inhibiting the phosphorylation of IκBα and the activation of the NF-κB pathway, thereby further regulating the decrease of the expression levels of caspase-1 and IL-1β, and inhibiting inflammation." (PMID 37372566, 2023). "The mentioned findings denote that inhibition of the NLRP3/caspase-1 and NF-κB channels, at least partially, facilitates he ameliorative effects of PAE against gastric ulcer triggered by ethanol." (PMID 34975497, 2021).
intracerebral hemorrhage (6 papers, 2019 to 2025). A cerebrovascular disorder characterized by bleeding into one or both cerebral hemispheres including the basal ganglia and the cerebral cortex. "Mechanistically, silencing P2X4 blocks the NLRP3/caspase- 1 pathway, demonstrating a neuroprotective effect in an intracerebral hemorrhage mouse model, while administration of an NLRP3 activator induces neuronal impairment in the same model." (PMID 40329125, 2025). "This study is performed to explore the role of P2X4 in intracerebral hemorrhage (ICH) and the association between P2X4 and the NLRP1/Caspase-1 pathway." (PMID 37652931, 2023). "MCC950 preserves the blood–brain barrier (BBB) and decreases cell death by downregulating NLRP3, caspase-1, and IL-1β production in mice with intracerebral hemorrhage." (PMID 35219323, 2022). "Ac-YVAD-cmk is an irreversible tetrapeptide inhibitor of caspase-1 with good cell permeability and protects the brain against injury induced by the stimuli such as intracerebral hemorrhage." (PMID 32703306, 2020).
lymphoma (6 papers, 2014 to 2025). A malignant (clonal) proliferation of B- lymphocytes or T- lymphocytes which involves the lymph nodes, bone marrow and/or extranodal sites. "To test whether BAFF activated through proteolytic processing of pro-caspase-1 and pro-IL-1β, we treated two lymphoma cell lines and primary B cells with different concentrations of BAFF." (PMID 33004801, 2020). "The activation of NLRP3 may increase the expression of NLRP3-related genes such as IL-18, IL-1β, NLRP3 and caspase-1 in lymphoma cells, thereby promoting proliferation, inhibiting apoptosis, and reducing the anti-tumor effect of dexamethasone." (PMID 29312552, 2017). "Our study found that the expression levels of NLRP3-related genes IL-18, IL-1β, NLRP3 and caspase-1, were increased after addition of ATP plus LPS, suggesting NLRP3 could be primed and activated in lymphoma cells." (PMID 29312552, 2017). "The researchers reported significantly higher mRNA expression for P2X7R, NLRP3, caspase-1, IL-18, and IL-1β in patients with SS who developed MALT-NHL over the follow-up, compared to both SS patients who did not develop lymphoma and controls." (PMID 38397043, 2024).
non-alcoholic fatty liver disease (6 papers, 2018 to 2025). "Hepatocellular NLRP3 inflammasome activation and caspase-1-mediated pyroptosis play a crucial role in the progression of non-alcoholic fatty liver disease (NAFLD)." (PMID 35707547, 2022). "Beyond immune cell-mediated liver injury, hepatocytes in patients with non-alcoholic fatty liver disease (NAFLD) and alcoholic steatohepatitis can directly activate the NLRP3-caspase-1 or DAG-PKCδ-NLRC4 inflammasomes, inducing pyroptosis." (PMID 39994107, 2025).
osteoporosis (6 papers, 2021 to 2025). A condition of reduced bone mass, with decreased cortical thickness and a decrease in the number and size of the trabeculae of cancellous bone (but normal chemical composition), resulting in increased fracture incidence. "The activated NOD-like receptor family pyrin domain-containing protein 3 (NLRP3) inflammasome is an important player in aging-related chronic diseases like osteoporosis, especially because of the causal caspase-1 activation and its correlation to adipose accumulation in bone tissues." (PMID 35308164, 2021). "When rats with OA were treated with anti-inflammatory and anti-osteoporosis drugs, caspase-1-dependent pyroptosis induced by the NLRP3 inflammasome was attenuated, suggesting the pernicious role of pyroptosis in OA." (PMID 38934781, 2024). "Further, in vivo and in vitro studies confirmed that OC-Exo-packaged miR-30a-3p was transferred to OBs and inhibited bone formation, possibly via targeting IKBKG to initiate caspase-1 activation and the secretion of IL-1β and IL-18, thus accelerating the progression of osteoporosis." (PMID 40110632, 2025). "Osteoporosis has a destructive effect on bone tissue through different mechanisms: nuclear factor-κβ ligand and NLRP3/Caspase-1/IL-1β cascade." (PMID 38759999, 2024).